IL4 (interleukin 4)
Diseases named in the same sentence as IL4 in open-access papers (continued):
Sharing a sentence is not in itself a finding about the gene and the disease.
keloid (10 papers, 2020 to 2026). An irregularly shaped, elevated mark on the skin caused by deposits of excessive amounts of collagen during wound healing. "Expression levels of IL-4 and IL-13 tended to be higher in the peripheral regions compared to the central regions of both anterior chest and auricular keloids." (PMID 40830367, 2025). "To investigate pruritus mediators in keloids, we analysed the Th2 cytokines, IL-4, IL-13, and IL-31, and SP neuropeptide gene expression in anterior chest keloids, ear keloids, and normal skin using real-time PCR." (PMID 40830367, 2025). "It is evident from the literature that the TH2 inflammatory axis plays an integral role in keloid pathogenesis, with IL‐4 and IL‐13 serving as key mediators." (PMID 39895409, 2025). "The expression of IL-4 was significantly different between patients with a family history of keloids and those with sporadic keloids." (PMID 39799030, 2025). "Other cytokines, such as IL33, IL-13, IL-10 and IL-4 have also been noticed increased in keloids." (PMID 41556665, 2026). "The high expression of IL-4 in the family history group may be of key importance in explaining why keloids run in families." (PMID 39799030, 2025). "In addition, increased expression of IL-4 and IL-13 was observed in the peripheral regions of keloids." (PMID 40830367, 2025). "Above all, dupilumab, which targets the IL-4/IL-13 pathway, may provide a better treatment choice for keloid patients, especially those with concurrent AD, and is worthy of further large-scale clinical trials." (PMID 37895153, 2023). "This evidence suggests that Th2 cells and their cytokines, especially IL-4 and IL-13, contribute to keloid development, and the Th2 axis may become a breakout area of research in keloid pruritus treatments." (PMID 37895153, 2023). "Th2 cells also mediate pruritus in keloids by producing IL-4 and IL-13." (PMID 37895153, 2023). "The increased expression of IL-4 in the keloid microenvironment may be the factor for CD8+ T cells stimulation and proliferation." (PMID 36012134, 2022). "Numerous cytokines, such as IL-4, IL-6, IL-10, IL-12, IL-13, IL-17, TNF-α, and TGF-β, are markedly elevated in the keloid local microenvironment." (PMID 37895153, 2023). "Interleukin 4 and IL‐13 (TH2 response) are overexpressed in patients with keloids." (PMID 39895409, 2025). "In addition, the factors related to Th1, Th2, and Th17 cells such as IL4/IL13, IL17A/IL22, ADAM33, IFN-γwere upregulated overall in keloid and AD." (PMID 38476235, 2024). "IL-4 and IL-13 not only promote ECM deposition, inflammation, and pruritus of keloids but also induce the transformation of monocytes into M2 macrophages, thus playing a pivotal role in the pathogenesis of keloids." (PMID 37895153, 2023).
nephrotic syndrome (10 papers, 2017 to 2025). A collection of symptoms that include severe edema, proteinuria, and hypoalbuminemia; it is indicative of renal dysfunction. "Several studies have correlated genetic variations of IL-4 gene and predisposition to a subtype of nephrotic syndrome—minimal change nephrotic syndrome (MCNS)—and consider these variants predictors for frequently relapsing childhood SSNS." (PMID 35208588, 2022). "The IL-4 polymorphism rs2243250 was associated with nephrotic syndrome and an increased risk of steroid resistance." (PMID 29549463, 2019). "Several studies have been conducted to investigate the role of polymorphisms in the genes coding for IL-4, IL-6, and IL-13 in pediatric patients with nephrotic syndrome." (PMID 29549463, 2019). "Interleukin-4 (IL-4) expression is implicated in the pathogenesis of nephrotic syndrome (NS)." (PMID 33535372, 2021). "Another study revealed increased levels of IL-4 in relapse of nephrotic syndrome and slightly lower in disease remission." (PMID 39996798, 2025). "In the nephrotic syndrome model group, renal IL-4 levels were significantly increased compared to the negative control group." (PMID 40149694, 2025). "This study demonstrates that the administration of Physalis angulata in a nephrotic syndrome model leads to a significant reduction in both IgG anti-nephrin and IL-4 levels compared to the nephrotic syndrome model group without treatment." (PMID 40149694, 2025). "GSEA analysis revealed that the FSTL1 high-expression group was mostly concentrated in pathways like primary focal segmental glomerulosclerosis (FSGS), nephrotic syndrome, and IL-4 and IL-13 signaling and neutrophil degranulation." (PMID 38390317, 2024). "It has been reported that children with nephrotic syndrome who had higher initial serum IgE levels, had higher relapsing rates, longer duration of steroid therapy before remission and higher serum IL-4 and IL-5 levels." (PMID 33330285, 2020). "Renal IL-4 levels in all treatment groups, including prednisone, Physalis angulata, and Physalis angulata + prednisone, were significantly decreased compared to the nephrotic syndrome model group." (PMID 40149694, 2025). "A mechanism whereby excess IL-13 might induce nephrotic syndrome is illustrated by changes in podocyte protein trafficking and proteolytic enzyme secretion seen when these cells are incubated with IL-4 or IL-13 in vitro." (PMID 33330285, 2020). "Cytokine gene polymorphism including that of IL-4 and IL-13 in nephrotic syndrome of children with an Arab race has not been explored previously." (PMID 33330285, 2020). "Th2 cytokines (Interleukin (IL)-13, IL-4, IL-5) are increased in patients with nephrotic syndrome, and changes in vascular permeability have been reported, which are both involved in the complex pathogenesis of proteinuria in nephrotic syndrome." (PMID 31208104, 2019). "This study aims to evaluate the effects of Physalis angulata extracts on anti-nephrin IgG, IL-4, and podocytopathy through BAFF inhibition in a doxorubicin-induced nephrotic syndrome rat model." (PMID 40149694, 2025). "Furthermore, Buffalo/Mna rats were characterized by Th2 polarization and presented a predominant increase in IL4 and IL13 levels, preceding the development of nephrotic syndrome." (PMID 29942802, 2018). "Furthermore, the administration of Physalis angulata also affected the renal IL-4 levels, which were significantly elevated in the nephrotic syndrome model group without treatment." (PMID 40149694, 2025). "A selective IL13-Th2 profile characterized children with nephrotic syndrome, who also presented upregulation of IL13 (but not IL4) mRNA by CD4+ and CD8+ cells during relapse." (PMID 29942802, 2018).
pemphigus (10 papers, 2016 to 2026). Pemphigus is a group of rare autoimmune diseases that cause blistering of the skin and mucous membranes (mouth, nose, throat, eyes, and genitals).This conditioncan occur at any age, but often strikes people in middle or older age. "A previous study showed that increased IL-4 and IL-10 are involved in T cells induction and autoimmune phenomena of pemphigus vulgaris and pemphigus foliaceous." (PMID 41446688, 2026). "Although IL-4 production has been noted following COVID-19 vaccination, there is a lack of data regarding the levels of IL-17 and IL-21 in individuals who develop pemphigus post-vaccination." (PMID 39203983, 2024). "Historically, it was assumed that autoantibody-mediated diseases like pemphigus were driven by classical T helper 2 (Th2) cells producing the lineage-characteristic cytokine interleukin 4 (IL-4)." (PMID 38393106, 2024). "Except for that, the latest research implicates that not only IL-4, but also IL-17 and IL-21 are closely correlated to the onset of autoimmune disorders like pemphigus." (PMID 35887732, 2022). "Another widely-acknowledged pathogenesis of pemphigus is that the disease is partially mediated by classical TH2 cells which produce lineage-specific cytokines such as IL-4 and IL-5." (PMID 35887732, 2022). "Upregulation of the Th2 cytokines IL-4, IL-5, IL-10, and IL-13 has been described in pemphigus patients." (PMID 27304671, 2016). "Dupilumab, a fully human mAb directed against the IL-4Rα blocking IL-4 related to IL-13 signaling, could be a therapeutic option for pemphigus." (PMID 35783635, 2022). "IL-4 is a key cytokine that is supposed to play a critical role in pemphigus." (PMID 35783635, 2022). "The pathogenesis of pemphigus involves a complex interaction among TH2, TH17, and TFH17 cells, with significant roles played by IL-4, IL-17, and IL-21." (PMID 39203983, 2024). "Pemphigus is a TH2 cell-driven disease, a complex TH17/TFH17 cell–dominated disease, and these cells produce lineage-specific cytokines like IL-4, IL-5, IL-17, and IL-21, and desmoglein-specific antibodies." (PMID 37496035, 2023).
SARS-CoV infection (10 papers, 2008 to 2023). "In one study of 128 convalescent patients with SARS-CoV infection, effective T cell responses were shown to be significantly associated with higher neutralizing antibody and with more serum Th2 cytokines (IL-4 and IL-10) detected in fatal group." (PMID 34341947, 2021). "During the process of SARS-CoV infection, there was a cytokine storm in patients including IL-1, IL-2, IL-4, IL-6, IL-8, IL-10, IFN-γ, TNF-α and TGF-β1." (PMID 18312678, 2008). "Abnormalities in the production levels of several cytokines such as IL-1, IL-2, IL-4, IL-6, IL-8, IL-10, IFN-γ, TNF-α and TGF -β1 were detected in patients with SARS-CoV infection." (PMID 32917282, 2020).
thyroid cancer (10 papers, 2015 to 2025). "By analyzing microarray data from the GEPIA database, we also found that POSTN levels were positively correlated with STAT3 and IL-4 is strongly linked to STAT6 in thyroid cancer." (PMID 38773979, 2024). "Likewise, M2-like tumor-associated macrophages polarized by IL-4/IL-13 promote stemness and metastasis of thyroid cancer cells by secreting IGF-I and IGF-II." (PMID 34769439, 2021). "The KEGG enrichment analysis revealed that the Thyroid cancer signaling pathway was significantly enriched in the downregulated genes of both the IL-4 and LPS treatment groups." (PMID 39908200, 2025). "IL-4 and IL-10 protect thyroid cancer cells from cytotoxic effect of antineoplastic drugs by induce the expression of Bcl-xL and Bcl-2." (PMID 32655554, 2020). "IL4 and IL-10 plays significantly role in protecting thyroid cancer cells from apoptosis when complicated with Graves' disease." (PMID 32655554, 2020). "On the contrary, IL-4 weakly stimulates the proliferation of thyroid cancer and protects it from apoptosis." (PMID 32655554, 2020). "They designed the IL4-Pseudomonas exotoxin (IL4-PE) conjugate and the treatment of IL4-PE decreased the colony formation ability of thyroid cancer cells and tumor growth in thyroid xenograft tumor model." (PMID 31540495, 2019). "An autocrine production of IL-4 and IL-10 has also been reported in thyroid carcinoma cells, promoting resistance to Fas-induced apoptosis through the activation of JAK/STAT pathways." (PMID 25793261, 2015). "Besides, autocrine production of IL-4 and IL-10 induces the over-expression of Bcl-xL and Bcl-2, two anti-apoptotic proteins, which subsequently protect thyroid cancer cells from the cytotoxic effects of antineoplastic drugs." (PMID 32655554, 2020). "Autocrine of IL-4 and IL-10 in thyroid cancer results in resistance to CD95-mediated apoptosis." (PMID 32655554, 2020). "IL-4 has been described as a growth factor of thyroid cancer cells." (PMID 26274317, 2015).
vitamin D deficiency (10 papers, 2013 to 2025). A nutritional condition produced by a deficiency of VITAMIN D in the diet, insufficient production of vitamin D in the skin, inadequate absorption of vitamin D from the diet, or abnormal conversion of vitamin D to its bioactive metabolites. "Unlike the uniformly risk-amplifying effects of Th2-pathway variants (IL4R/IL-4/IL13) under vitamin D deficiency, MS4A2’s role is protective and vitamin D-dependent." (PMID 40927566, 2025). "Strong evidence substantiates that vitamin D deficiency during pregnancy caused an imbalance in the Th1/Th2 ratio, decreased IFNγ production, but increased IL-4 concentration." (PMID 41010514, 2025). "The relationship between vitamin D deficiency and levels of IL-1β, IL-4, and IL-6 was previously shown in obese rats fed a vitamin D-reduced high-fat diet." (PMID 39310506, 2024). "Furthermore, gestational vitamin D deficiency is considered to increase IL4 concentration and decrease the Th1/Th2 ratio and IFNG production." (PMID 37520545, 2023). "Particularly, we suggest that since IL-31 is likely to be expressed by a number of cells in the allergic situations in which IL-4 is present and promotes Th2-driven inflammation, it contributes in allergic reaction involving the vitamin D deficiency only partially." (PMID 25061262, 2014). "Vitamin D deficiency shifts this system toward a pro-inflammatory state that favors Th1 and Th17 activation and increased expression of TNF, IFNγ, and IL-17, as well as elevated expression of pro-inflammatory Il-4, IL-5 and IL-13, and gut barrier dysfunction." (PMID 32093192, 2020). "As observed previously with higher doses of OVA/Alum, vitamin D deficiency enhanced the capacity of ADLN cells to proliferate and secrete cytokines like IL-4, IL-5, IL-10 (data not shown), but not IL-6, IL-17, TNF or IFNγ (data not shown)." (PMID 23826346, 2013).
autoimmune myocarditis (9 papers, 2012 to 2025). Autoimmune myocarditis is an autoimmune disease that affects the heart. "It was also observed that in case of severity of experimental autoimmune myocarditis inhibition of IL-4 with anti-IL-4 monoclonal antibody reduced the severity of disease." (PMID 29675022, 2018). "Treatment with pioglitazone increased expression levels of IL-4 in a model of autoimmune myocarditis, and there was an amelioration of the inflammation." (PMID 23983678, 2013). "Treatment with pioglitazone changes the helper T-cell balance from Th1 to Th2 in the myocardium of rats with autoimmune myocarditis by upregulating the mRNA of Th2 cytokine IL-4 and by reducing the mRNA level of Th1 cytokine IFN-γ." (PMID 23983678, 2013). "Evidence so far suggests that IL-4 increases autoimmune myocarditis by elevating autoantibody production and activating mast cells and alternatively activated macrophages that produce cytokines and enzymes needed for remodeling and fibrosis." (PMID 22013485, 2012). "Anti-IL-4 monoclonal antibodies reduce the severity of experimental autoimmune myocarditis." (PMID 39011048, 2024). "However, a contradictory finding was reported in the context of autoimmune myocarditis, where eosinophils are the predominant cell type in the heart expressing IL-4, and eosinophil-specific IL-4 deletion leads to improved cardiac function." (PMID 37047468, 2023). "In an mice model of experimental autoimmune myocarditis (EAM), researcher found that the generation of IFN-γ was significantly increased, while the generation of IL-4 was markedly declined compared with the control group." (PMID 32765268, 2020).
brain injury (9 papers, 2019 to 2026). Acute and chronic (see also brain INJURIES, CHRONIC) injuries to the brain, including the cerebral hemispheres, CEREBELLUM, and brain STEM. "After a single mild traumatic brain injury, interleukin-10, interleukin-13, interleukin-4 and tumour necrosis factor-alpha were elevated 3 days post-injury while interleukin-10 and tumour necrosis factor-alpha levels were elevated 14-days post-injury." (PMID 41675431, 2026). "For example, individual monocytes/macrophages demonstrated enrichment of both “M1-like” (IFN-γ and LPS) and “M2-like” (IL-4) signatures following traumatic brain injury." (PMID 34054608, 2021). "However, upon brain injuries, MGs became active and highly proliferate due to several factors (e.g., IL-1β, IL-4, Tnf-α, and GM-CSF)." (PMID 36675286, 2023). "It has been found that immunomodification of MSCs to express IL-4 could promote M2 microglia/macrophage polarization, functional recovery, and inhibit neuroinflammatory responses after brain injury." (PMID 36181630, 2023). "However, despite an increasing body of evidence supporting the beneficial effects of IL-4 in neurological diseases, the effect of IL-4 in hypoxia-induced brain injuries is under debate." (PMID 32982939, 2020). "While normal levels of IL-4 may have neuroprotective effects, high levels of this cytokine are observed in extreme situations, such as traumatic brain injury." (PMID 31428001, 2019).
cognitive decline (9 papers, 2013 to 2025). "The authors concluded that microglial activation is a major causal factor, as its removal prevented cognitive decline and reduced a broad spectrum of cytokines (IL-1α, IL-1β, IL-3, IL-4, IL-5, GM-CSF)." (PMID 41155372, 2025). "Specifically, we found a significant increase in the levels of IL-4 (p = 0.024), IL-10 (p = 0.040) and G-CSF (p = 0.046) in AD patients with a fast cognitive decline compared to slow cognitive decline in ADAS-cog over one year." (PMID 23762274, 2013). "Interestingly, other experimental evidence suggests that elevated IL-4 levels demonstrated hippocampal neuroinflammation and cognitive decline in a mouse model." (PMID 31901235, 2020). "Speculatively, a functional compromise in IL-4 protective effect on hippocampal circuits in AD could lead to a compensatory increase in levels, and indeed, peripheral IL-4 and IL-10 were both highly elevated only in subsets of AD patients with more rapid cognitive decline." (PMID 39071802, 2024). "AD patients with intermediate cognitive decline showed significantly higher levels of IL-2 (p = 0.021), IL-4 (p = 0.016), IFN-γ (p = 0.018) and PDGF (p = 0.031) compared to those with slow cognitive decline over one year." (PMID 23762274, 2013).